VAV2 (vav guanine nucleotide exchange factor 2)
Diseases named in the same sentence as VAV2 in open-access papers (continued):
Sharing a sentence is not in itself a finding about the gene and the disease.
endometrial carcinoma (1 paper, 2018). A malignant tumor arising from the epithelium that lines the cavity of the uterine body. "Because all Vav1, Vav2, and Vav3 were detected by RT-PCR in our endometrial carcinoma cell lines (data not shown), functional compensation may have occurred." (PMID 29872505, 2018).
escherichia coli infection (1 paper, 2013). Infection with the organism Escherichia Coli. "PRKC (including PRKCA and PRKCB), along with VAV (VAV2 and VAV3) genes also feature in various high ranking immunological pathways including T cell signaling, Pathogenic Escherichia Coli Infection and Natural Killer Cell Mediated Cytotoxicity." (PMID 24278029, 2013).
esophageal squamous cell carcinoma (1 paper, 2021). Esophageal squamous cell carcinoma (ESCC) is a type of esophageal carcinoma (EC) that can affect any part of the esophagus, but is usually located in the upper or middle third. "Here, using esophageal squamous cell carcinoma (ESCC) as a model, we demonstrate that guanine nucleotide exchange factor 2 (VAV2), which is overexpressed in most human cancers, plays an important role in primary and secondary radioresistance." (PMID 34462423, 2021).
hereditary cancer (1 paper, 2020). Malignant neoplasms occurring in families at a rate greater than that expected by chance and caused by germline mutations in a specific gene. "The results obtained with the Vav2Onc/Onc mouse strain in the present study suggest that this gain-of-function VAV2 mutation, in combination with other genetic alterations, should contribute to the etiology of this type of hereditary cancers." (PMID 32963234, 2020). "In addition, they provide a pathobiological framework to understand the contribution of mutant VAV2 to this rare hereditary cancer." (PMID 32963234, 2020).
Hyperinsulinemia (1 paper, 2020). An increased concentration of insulin in the blood. "Our study demonstrated that EMP treatment significantly improved hyperinsulinemia and increased the expression level of Vav2 in T2D rats." (PMID 32256445, 2020).
invasive breast carcinoma (1 paper, 2017). A carcinoma that infiltrates the breast parenchyma. "Oncoprints showed alterations (amplification, deep deletion, mRNA upregulation truncating mutation and missense mutation) of TIAM1 and VAV2 genes in invasive breast carcinomas and TNBC data sets." (PMID 27902969, 2017).
lymph node metastasis (1 paper, 2025). "Additionally, a significant association was observed between VAV2 levels and lymph node metastasis." (PMID 40303312, 2025).
medulloblastoma (1 paper, 2022). A malignant, invasive embryonal neoplasm arising from the cerebellum. "Moreover, the up-regulated phosphorylation levels of Vav2 were further verified in medulloblastoma tissues from GFAP-Cre;SmoM2 +/- mice as well as in human clinical Shh type MB samples." (PMID 35154488, 2022).
multiple sclerosis (1 paper, 2022). A progressive autoimmune disorder affecting the central nervous system resulting in demyelination. "In the “inhibition of remyelination in multiple sclerosis: regulation of cytoskeleton proteins”, MAPT—in which Fyn suppression inactivates the guanine nucleotide exchange factor Vav 2 via CDC42—destabilizes the actin microfilaments." (PMID 35804531, 2022).
nephrotic syndrome (1 paper, 2024). A collection of symptoms that include severe edema, proteinuria, and hypoalbuminemia; it is indicative of renal dysfunction. "Immunofluorescence microscopy of Sh2bp2KI/KI mouse kidneys validated the importance of PLCγ2 and VAV2 downstream of SH3BP2 in nephrotic syndrome as suggested by in silico IMPRes analysis of human glomerular transcriptome." (PMID 38127456, 2024). "Human glomerular transcriptome data suggest that SH3BP2 recruits PLCG2 and VAV2 in downstream signaling in nephrotic syndrome." (PMID 38127456, 2024). "We used human transcriptomic and clinical data from the Nephrotic Syndrome Study Network (NEPTUNE) to demonstrate that SH3BP2, its partner molecules (especially PLCγ2 and VAV2), and innate immune signaling pathways are upregulated in the glomerular transcriptome in nephrotic syndrome." (PMID 38127456, 2024).
pancreatic cancer (1 paper, 2015). "For instance, specific depletion of only Vav1 in pancreatic cancer cell lines led to inhibition of their growth, despite the continuous expression of Vav2." (PMID 26353933, 2015). "Thus, reduction of Vav2 and Vav3 expression in mouse mammary tumor cells led to a decline in metastatic growth, similar to the effect of Vav1 depletion in pancreatic cancer cells." (PMID 26353933, 2015). "Moreover, knockdown of Vav2 in these cells did not alter their growth, suggesting that Vav1 and Vav2 play different roles in pancreatic cancer cells." (PMID 26353933, 2015).
psoriasis (1 paper, 2020). An autoimmune condition characterized by red, well-delineated plaques with silvery scales that are usually on the extensor surfaces and scalp. "However, the elevation in VAV2 transcripts is much less noticeable in skin samples from psoriasis patients." (PMID 32963234, 2020).
Salmonella Infections (1 paper, 2015). Infections with bacteria of the genus SALMONELLA. "Our study shows that VAV2 is significantly down-regulated after Salmonella infection in vivo and that it can be targeted by miR-331-3p in vitro." (PMID 26227241, 2015).
Sepsis (1 paper, 2024). Sepsis is defined as life-threatening organ dysfunction caused by a dysregulated host response to infection. "We identified significant upregulation of NTSR1, BCL6, ZDHHC19, MGLL, and ALPK1 in sepsis compared to healthy individuals, while VAV2 and SATB1 were significantly downregulated in sepsis." (PMID 38167131, 2024). "The observed significant upregulation of NTSR1, BCL6, ZDHHC19, MGLL, and ALPK1 in sepsis compared to healthy individuals, along with the notable downregulation of VAV2 and SATB1 in sepsis, provides a comprehensive picture of the altered gene expression landscape during sepsis." (PMID 38167131, 2024). "Additionally, bulk RNA analysis revealed significant increases in NTSR1, BCL6, ZDHHC19, MGLL, and ALPK1 in sepsis, and significant decreases in VAV2 and SATB1 in sepsis; FCHO1 showed a significant decrease in sepsis patients who did not survive compared to those who survived at 28 days." (PMID 38167131, 2024).
thyroid cancer (1 paper, 2024). "These hub genes identified in our study have implications for the response to immune checkpoint inhibitors therapy (PRKDC) and offer potential prognostic markers (CUL1, VAV2), presenting a novel avenue or additional treament for thyroid cancer therapeutics." (PMID 39013964, 2024).
type 1 diabetes (1 paper, 2012). "However, it has been proposed as the candidate gene in the Idd18.1 region linked with type 1 diabetes in mouse, and the Vav1/Vav2/Vav3 family is necessary for adaptive immune function in mouse." (PMID 22493691, 2012).
tumor (37 papers, 2009 to 2026). "Taking together, the upregulation of VAV2 catalytic activity facilitates tumor development, similar to the effect caused by some VAV1 mutations in PTCLs." (PMID 34571765, 2021). "Among the 19 pairs of normal-tumor cases, the somatic mutation frequencies of these genes ranged from 5.3 to 36.8%, with VAV2, TBC1D10C, KIAA0556, and IQGAP1 showing the highest mutation frequencies (green box)." (PMID 31798960, 2019). "VAV2 is seldom mutated in hnSCCs according to cBioPortal-archived cancer genome data, indicating that the overexpression of the WT protein will be the most relevant type of deregulation found for this pathway in this tumor type." (PMID 32963234, 2020). "In addition, Vav3 is implicated in receptor-triggered angiogenesis, and host deficiency in Vav2/Vav3 retards tumor growth based on impaired vascularization within the tumor bed." (PMID 30083818, 2018). "VAV2 exhibited consistent upregulation at both mRNA and protein levels in tumor tissues (P < 0.0001)." (PMID 42201473, 2026). "IHC staining and Western blot analysis further demonstrated that VAV2 and Ki67 expression levels correlated with tumor size." (PMID 40303312, 2025). "In vivo, VAV2 depletion in C4-2 xenografts resulted in reduced tumor growth, as evidenced by decreased tumor volume and weight." (PMID 40303312, 2025). "Tumor growth was significantly inhibited in the VAV2-knockdown group, with further suppression observed upon Enzalutamide treatment." (PMID 40303312, 2025). "TIMER2.0 analysis revealed significantly elevated VAV2 expression across multiple tumor types, including PCa." (PMID 40303312, 2025). "In HNC, dysregulation of GNRF, particularly Vav2, can lead to the abnormal activation of GTPases, promoting tumor progression through altered signaling pathways, ribosome biogenesis, invasion, immunosuppression, and metastasis." (PMID 39628997, 2024). "The expression level of VAV2 in tumor tissues of TC patients is higher than that in adjacent tissues." (PMID 35528244, 2022). "Activation of the phosphorylated form of VAV2 has been reported in highly invasive tumor cell lines." (PMID 35528244, 2022). "We have shown before that Vav2 plays pro-tumorigenic roles in this tumor using pathways like those found in skin keratinocytes." (PMID 35534539, 2022). "VAV2 is involved in the formation of filamentous pseudopodia, lamellar pseudopodia, and membrane folds of tumor cells and regulates the migration and infection of tumor cells." (PMID 35528244, 2022). "In this study, we have identified for the first time that VAV2 is required for DNA NHEJ repair and, thus, its overexpression is implicated in resistance of tumor to radiotherapy." (PMID 34462423, 2021). "In the present study, taken ESCC as a study model, we have identified VAV2 as a key player for radioresistance via integrative analysis of genes associated with radioresistance in mouse PDX models and genes overexpressed in tumor." (PMID 34462423, 2021). "The stronger interaction of VAV2 with Ku70/Ku80 was also evident in clinical ESCC tumor specimens compared with adjacent normal tissues as shown by multiple immunofluorescent staining." (PMID 34462423, 2021). "Consistent with this, we have demonstrated that the upregulation of VAV2 catalytic activity promotes the development of a hyperplasic phenotype that, when combined with additional genetic lesions, facilitates tumor development and progression." (PMID 32963234, 2020). "Our study is the first report presenting that RAC1-activation via beta-catenin-VAV2/TIAM1 cascade acts as a downstream signaling event of WP activation in TNBC in the regulation of fibronectin-directed MA tumor cell phenotypes." (PMID 27902969, 2017). "We report for the first time that RAC1-activation via beta-catenin-TIAM1/VAV2 cascade acts as a downstream signaling event of WP activation in TNBC in the regulation of fibronectin-directed MA tumor cell phenotypes." (PMID 27902969, 2017).
tumor (continued). "Consistent up-regulation of VAV1 and VAV2 observed across all tumours, was also replicated in a previous report." (PMID 28886030, 2017). "The knockout mice had a 2-fold reduction in total tumors, indicating that the knocked out genes (Vav2 and Vav3), were important to tumor formation." (PMID 23935452, 2013). "Despite the large number of Rho GEFs present in both normal and tumoral epidermis, we demonstrate that the co-expression of the exchange factors Vav2 and Vav3 is critical for the development of this tumor type." (PMID 23935450, 2013). "VAV2 protein functions as a guanine nucleotide exchange factor and scaffold protein to activate Rho/Rac family GTPases which play important role in cytoskeleton reorganization and tumor progression." (PMID 36631800, 2023). "An important issue to be further addressed in the near future is to verify the relevance of the VAV1-dependent tumor suppressor function in VAV2- and VAV3-driven tumors, particularly in those that may be NOTCH1-dependent." (PMID 34571765, 2021). "Furthermore, we have demonstrated that the VAV2 expression level in tumor is a potential biomarker for predicting radiosensitivity." (PMID 34462423, 2021). "By contrast, the Vav2/Vav3-dependent gene signature was found conserved in fully developed tumors, indicating that it may also play roles in tumor maintenance and/or progression." (PMID 23935452, 2013). "The team also showed that TPA has a different effect on wild-type and knockout mice; knockouts do not have the normal proliferative and inflammatory responses to the chemical, indicating that Vav2 and Vav3 are needed for these responses and subsequent tumor formation." (PMID 23935452, 2013). "We think that this newly identified interaction provides a possible explanation on the signaling pathways in which KCC3 and KCC4 overexpression might lead to accentuated tumor cell invasion and malignancy through the collaboration of KCCs with Vav2 in cancer cell biology." (PMID 23724134, 2013). "After the SH intervention, the levels of the tumor angiogenesis-related genes MMP-2, VEGFA, VEGFC, VAV2, and LARP1 were significantly downregulated when compared with the Model group, whereas the GADD45A level was markedly upregulated." (PMID 41444284, 2025). "Numerous studies discriminated that VAV2 is a protooncogene of the VAV family, and has been found critical to Rho GTPase activity in tumor development and maintenance." (PMID 36426134, 2022). "This study found that TC exosomes regulate the miR-6838-5p/VAV2 axis through FGD5-AS1, promoting tumor angiogenesis and vascular permeability." (PMID 35528244, 2022). "Many genes in these chromosome regions, such like ERLIN2 (amp 8p11.23), VAV2 (del 9q34.2), ADAMTS6 (del 5q12.3) and NCS1 (del 9q34.11), are known to be related with tumor invasion and metastasis." (PMID 33193655, 2020). "VAV2 (DBL family of proteins) is a ubiquitous guanine nucleotide exchange factor for the small GTPase RAC1 and extensively studied for its role in neurite outgrowth and branching and tumor cell invasion." (PMID 38127456, 2024). "In addition, we found that the expression levels of VAV2, CD34, VEGF, and VE-cadherin in tumor tissues of the AKT18FGD5-AS1-Exos group were upregulated." (PMID 35528244, 2022). "This is in agreement with previous studies indicating that the combined elimination of Vav2 and Vav3 does not elicit any overt epidermal or skin defects in mice." (PMID 35534539, 2022). "In any case, this dysregulation seems to be rather specific since the expression of genes located in the vicinity of VAV2 do not exhibit any kind of dysregulation in the tumor expression datasets analyzed in this work." (PMID 32963234, 2020). "(iii) The inverse correlation found between the abundance of the NR2F1 mRNA and the transcripts for other signaling elements of the pathway under analysis in this work (VAV2, VAV3, and CDH1) in human tumor samples according to in silico coexpression matrix analyses." (PMID 30087437, 2019).
tumor (continued). "TNBC patients’ (cBioPortal) tumor expressed alterations of TIAM1 and VAV2 genes." (PMID 27902969, 2017). "In this study, we found that DCIS in patients whose tumor cells invaded into surrounding tissue had significantly increased levels of Vav2 protein expression compared to those that did not." (PMID 25785189, 2014). "In contrast to IGF-IR and Rap1, Vav2 protein expression remained non-elevated in noninvasive proliferative lesions found in the mammary gland such as DCIS until later stages of tumor progression to IBC." (PMID 25785189, 2014). "We next ascertained whether miR-148a-mediated down-regulation of PAI-1, VAV2, ITGA5, and ITGB8 expression resulted in the inhibition of malignant progression of tumor cells." (PMID 21703006, 2011). "This phenotype is specifically driven by the deficiency in this Vav family member, because we have not observed statistically significant increases in deaths/tumor rates in Vav2–/–, Vav3–/– or Vav2–/–;Vav3–/– mice when compared to control littermates." (PMID 20011522, 2009). "Despite this relevant difference, VAV proteins share a very similar structure and can exhibit overlapping functions, suggesting that VAV2 and VAV3 might play tumor suppressor roles similar to those carried out by VAV1 beyond the long-held signaling archetype for RHO GEFs." (PMID 34571765, 2021). "The abundance of VAV2, which is a guanine nucleotide exchange factor for small GTPases and is induced by steroidogenic factor-1, predicted the patient’s overall survival independent of age, tumor stage, and Ki-67 index." (PMID 34359790, 2021). "The correlation between VAV2 transcript levels and the c-MYC- and YAP/TAZ-regulated gene signatures is lost in most cases when the hnSCC samples are not stratified according to HPV status, further linking this Vav2Onc-driven pathobiological program to HPV– tumor cases." (PMID 32963234, 2020). "Likewise, phosphorylation of the direct SFK substrates p120-catenin, p130cas and Vav2 was observed at the invasive tumor edge but not in the tumor core." (PMID 23457577, 2013). "Because Vav2 was increased in IBC, but not in DCIS lesions, we hypothesized that change in Vav2 protein expression might be associated specifically with the onset of invasive potential in tumor cells, i.e. invasive tumor progression." (PMID 25785189, 2014). "It is also specific for the VAV2 locus, because the two genes that flank the VAV2 gene (SARDH, BRD3) do not show any consistent variation in expression in the human and mouse tumor datasets interrogated in this study." (PMID 32963234, 2020).